ISY1 (ISY1 spliceosome associated protein)
Description:
Component of the spliceosome C complex required for the selective processing of microRNAs during embryonic stem cell differentiation (By similarity). Required for the biogenesis of all miRNAs from the pri-miR-17-92 primary transcript except miR-92a (By similarity). Only required for the biogenesis of miR-290 and miR-96 from the pri-miR-290-295 and pri-miR-96-183 primary transcripts, respectively (By similarity). Required during the transition of embryonic stem cells (ESCs) from the naive to primed state (By similarity). By enhancing miRNA biogenesis, promotes exit of ESCs from the naive state to an intermediate state of poised pluripotency, which precedes transition to the primed state (By similarity). Involved in pre-mRNA splicing as component of the spliceosome.
Synonyms: KIAA1160; fSAP33
Tractability: Small molecule: a structure with a bound ligand is known. PROTAC: ubiquitination databases record sites on it; its protein half-life has been measured.
Gene: Protein-coding gene on chromosome 3 (129,127,415 to 129,161,349, reverse strand). Ensembl gene ENSG00000240682.
Subcellular location: Nucleus
Subcellular location (Human Protein Atlas): Nuclear speckles
Pathways (Reactome):
DNA Repair: Dual incision in TC-NER; Formation of TC-NER Pre-Incision Complex; Gap-filling DNA repair synthesis and ligation in TC-NER; Transcription-Coupled Nucleotide Excision Repair (TC-NER)
Disease: Dengue Virus-Host Interactions
Metabolism of RNA: mRNA Splicing - Major Pathway
Gene Ontology:
Molecular function: protein binding; RNA binding
Biological process: mRNA splicing, via spliceosome; generation of catalytic spliceosome for second transesterification step; mRNA 3'-splice site recognition
Cellular component: catalytic step 2 spliceosome; nuclear speck; nucleus; spliceosomal complex; U2-type catalytic step 1 spliceosome; nucleoplasm; post-mRNA release spliceosomal complex; post-spliceosomal complex; Prp19 complex
Genetic constraint (gnomAD): Loss-of-function variants: 12 observed, 55.23 expected, observed/expected ratio (o/e) 0.22, 90% interval 0.14 to 0.35. The upper end of that interval is the gene's LOEUF score, 0.35, which puts it in group 1 of 6, group 1 being the genes least tolerant of losing a copy. Missense variants: 282 observed, 354.9 expected, observed/expected ratio (o/e) 0.79, 90% interval 0.72 to 0.88. Synonymous variants: 96 observed, 123.47 expected, observed/expected ratio (o/e) 0.78, 90% interval 0.66 to 0.92.
Homologues: Orthologues: chimpanzee ISY1 (99% identical), macaque ISY1 (99% identical), guinea pig ISY1 (99% identical), dog ISY1 (98% identical), mouse Isy1 (98% identical), rabbit ISY1 (98% identical), rat Rab43 (88% identical), zebrafish isy1 (82% identical), pig ISY1 (71% identical), Drosophila melanogaster CG9667 (58% identical), Caenorhabditis elegans isy-1 (46% identical), tropical clawed frog isy1 (45% identical).
Diseases named in the same sentence as ISY1 in open-access papers:
ISY1 is named in the same sentence as 5 diseases in open-access papers, as found by Europe PMC text mining. Sharing a sentence is not in itself a finding about the gene and the disease. The quoted sentences say what the papers report.
cancer (3 papers, 2022 to 2025). A tumor composed of atypical neoplastic, often pleomorphic cells that invade other tissues. "These may suggest that longer transcripts of PABPN1, CCDC12 and ISY1 are important for maintaining cancer cell survival (p < 0.01)." (PMID 36263133, 2022).
tumor (3 papers, 2024 to 2025). "Studies have shown that pre-mRNA splicing factor 1 homologs (ISY1) are upregulated at both the transcriptomic and proteomic levels in the initiation, progression, and tumor stages of HCC." (PMID 40046230, 2025). "Seven genes passing these filters were involved in various aspects of tumour biology, including cell survival and DNA repair (CASP9, NDRG1, and XPA), mTOR signalling (TSC1), and transcription and RNA processing (ETV6, ISY1, and SMAD2)." (PMID 39660592, 2024).
ISY1 also shares sentences with these, for which no sentence is quoted: cervical cancer (1 paper); dilated cardiomyopathy (1); human papillomavirus infection (1).